TNF (tumor necrosis factor)
Diseases named in the same sentence as TNF in open-access papers (continued):
Sharing a sentence is not in itself a finding about the gene and the disease.
renal carcinoma (33 papers, 2009 to 2025). A carcinoma arising from the epithelium of the renal parenchyma or the renal pelvis. "In this study, we reanalyzed a TKI resistance dataset (GSE76068) and found that TNF and the NF-kappa B signaling pathway are very closely associated with sunitinib resistance in renal cancer." (PMID 35280681, 2022). "Subsequently, we revealed that downregulation of OTUD1 contributes to the sensitivity of renal cancer cells to TKIs, and this effect was blocked by TNF/NF-kappa B inhibitors and AKT inhibitors." (PMID 35280681, 2022). "NFAT1 improves the expression of PD-L1 by means of boosting TNF abundance in renal cancer to promote the proliferation of renal cancer cells and regulate immunoreaction via multiple signaling pathways." (PMID 35814468, 2022). "IL6 is the downstream gene of TNF signaling 13, and CBX7 contributes to the repression of TNF signaling in renal cancer cells." (PMID 35342353, 2022). "Not all of these cancers showed a correlation with survival and expression of TNF/LTA with the exception of renal carcinoma." (PMID 33546280, 2021). "VCAN knockdown significantly reduced the proliferation of renal cancer cells and increased apoptosis, which is linked to the changes of several TNF signaling related genes such as TNFα, BID and BAK." (PMID 33836688, 2021). "PrPC conveys TNF-α resistance in some renal cancers, and therefore, the coadministration of anti-PrPC antibodies improves chemotherapy." (PMID 34067472, 2021). "TNF‐α induces EMT in renal cancer via repressing the E‐cadherin expression and enhancing Vimentin and MMP‐9 expressions." (PMID 33159487, 2020). "In renal carcinoma cells, TNF increased the expression of GM2 by enhancing the mRNA level of B4GALNT1 encoding the GM2/GD2 synthase, and resulted in T cell death and immune dysfunction." (PMID 29698439, 2018). "Specifically, cordycepin inhibited TNF-α-mediated NF-κB activation, which induced renal cancer cell apoptosis." (PMID 29045468, 2017). "In the present study, we showed that the treatment of human renal cancer cells with cordycepin inhibited TNF-α-mediated NF-κB/GADD45B signaling, which upregulated the MKK7-JNK signaling pathway activation through inhibition of c-FLIPL expression." (PMID 29045468, 2017). "Its expression is activated by immunotherapeutic agents such as TNF-α, alone or in combination with other interleukins, in patients with renal cancer." (PMID 22028734, 2012). "Both TNF-α and its receptors are coexpressed by renal carcinoma cells and, upon binding, the expression of angiogenesis-related genes such as VEGF and IL-6 has been reported." (PMID 19904265, 2009). "TNF-α was selected because recent reports have demonstrated its involvement in renal carcinoma development, and targeted therapies using anti-TNF-α have been recently shown to be efficacious against this tumour." (PMID 19904265, 2009). "Treatment with TNF and NF-kappa B inhibitors sensitized renal cancer cells to sunitinib." (PMID 35280681, 2022). "In addition, several clinical trials have demonstrated the importance of TNFα blockade in prostate and renal cancer and in hematologic malignancies, as it promotes higher OS." (PMID 33540543, 2021). "Additionally, dysregulation of TNF-α has been detected in many cancers, such as ovarian and renal cancers, as well as in the serum of patients with cancer, but not in that of healthy individuals." (PMID 34948424, 2021). "Elevated TNF-α levels are found in several cancer tissues, such as ovarian and renal cancers 50,53." (PMID 33173438, 2020). "The potential involvement of TNF-α in renal cancer has been recently demonstrated." (PMID 19904265, 2009). "Commonly studied inflammatory markers such as CRP, IL-6, TNF-α, and procalcitonin (PCT) have all been associated with cancer-related inflammation CRP, for instance, is recognized as a prognostic marker in multiple malignancies, including pancreatic, breast, gastrointestinal, and renal cancers." (PMID 39594709, 2024).
renal carcinoma (continued). "Since the TNF signaling pathway is responsible for the regulation of tumor growth via activating NF-kappa B pathway in renal cancer and other types of malignant tumor 11, 12, we tested whether CBX7 inhibited tumor proliferation through inactivation of the TNF pathway." (PMID 35342353, 2022). "Also, TNF-α could strongly up-regulate CXCR3 to facilitate invasion and metastasis of renal carcinoma, and high expression of CXCR3 was associated with poor prognosis." (PMID 33324682, 2020). "Tumor necrosis factor-alpha (TNF-α) upregulates layilin expression in both chondrocytes and human renal carcinoma cells, whereas TGF-β lacks this effect in renal carcinoma cells." (PMID 41404063, 2025). "Then, RNA-seq data for CBX7 indicated that CBX7 inactivated the TNF pathway to block tumor growth and downregulated IL6 to sensitize renal cancer cells to TKIs." (PMID 35342353, 2022). "Recent data has shown that TNF-α significantly increased the expression of CXCR2 and CXCR3 and their related ligands in renal cancer cells enhancing the migration, invasion and EMT." (PMID 29416784, 2018). "It has been shown that TNFα stimulated EMT of human colonic organoids, promoted EMT in renal carcinoma cells and in human skin cells." (PMID 22675434, 2012). "Furthermore, RTN3, an ER-phagy receptor, is highly downregulated in hypoxic conditions, but its overexpression triggers tumor necrosis factor-α (TNF-α)-related apoptosis-inducing ligand (TRAIL) and the Fas-dependent apoptosis of renal cancer cells compared with normal cells." (PMID 36497032, 2022). "Thus, we aimed to study whether the effect of OTUD1 on the sensitivity of renal cancer cells to TKIs is mediated by the AKT and TNF/NF-kappa B signaling pathways." (PMID 35280681, 2022). "In addition, TNFα induced the upregulation of CXCL3 and its receptor in A498 renal cancer cells." (PMID 32986377, 2020).
soft tissue sarcoma (33 papers, 1996 to 2024). A malignant neoplasm arising from muscle tissue, adipose tissue, blood vessels, fibrous tissue, or other supportive tissues excluding the bones. "In contrast, localized TNF administration using isolated limb perfusion has yielded excellent effects in soft tissue sarcomas." (PMID 38338920, 2024). "The procedure was first described in 1952 and adapted by Eggermont in 1992 for the treatment of soft tissue sarcomas using melphalan and TNF-a." (PMID 37892681, 2023). "In contrast, localized administration of TNF-α in the form of isolated limb perfusion have yielded excellent results in soft tissue sarcomas." (PMID 35574362, 2022). "Recombinant tumor necrosis factor (TNF) in combination with melphalan has gained marketing authorization in Europe for the treatment of unresectable soft tissue sarcoma, in which TNF is administered through isolated limb perfusion procedure." (PMID 31803362, 2019). "From a clinical perspective TNF-alpha ILP therapy was approved in Europe for high grade soft tissue sarcoma in 1998." (PMID 30170620, 2018). "In contrast, localized administration of TNF-alpha in the form of isolated limb perfusion have yielded excellent results in soft tissue sarcomas." (PMID 30170620, 2018). "TIA-1, which encodes an RNA-binding protein with translation-regulatory functions has already been reported to be up-regulated in tumor specimens post-treatment with TNF alpha in soft tissue sarcomas." (PMID 18959781, 2008). "In the present study an isolated limb perfusion with TNF, actinomycin D or a combination in BN-175 soft tissue sarcoma bearing rats was performed to investigate the tumour response to these treatments." (PMID 11953868, 2002). "Recombinant TNFα is used in isolated limb perfusion for the treatment of soft tissue sarcomas." (PMID 38546220, 2024). "Also, TNF-α is now used in isolated limb perfusion for treatment of soft tissue sarcoma (STS) and other large tumors." (PMID 36092920, 2022). "The soft tissue sarcoma BN-175 used in this study was found to be susceptible to actinomycin D, but addition of TNF did not result in a more cytotoxic effect on these tumour cells." (PMID 11953868, 2002). "Hyperthermic isolated limb perfusion with tumor necrosis factor-α and melphalan (TM-HILP) has been successfully used to treat limb soft tissue sarcomas (STSs) with high response rates." (PMID 23938063, 2013). "We reported that administration of low-dose TNF-α, in combination with PEGylated liposomal doxorubicin (PLD), provided a significantly higher DXR delivery in soft tissue sarcoma in BN rats, resulting in a stable tumor volume compared to treatment without TNF-α." (PMID 36297598, 2022). "One of these treatment modalities is TM-ILP (TNF-melphalan-based isolated limb perfusion), which has developed into a successful treatment option for primarily non-resectable soft-tissue sarcoma of the extremities." (PMID 28403880, 2017). "BN-175 soft tissue sarcoma-bearing rats were perfused with different concentrations of actinomycin D or melphalan with or without TNF." (PMID 11953868, 2002). "Moreover, regional administration of L-NAME, in combination with TNF and melphalan, was studied in an isolated limb perfusion (ILP) model using BN175 soft-tissue sarcomas." (PMID 11027431, 2000). "An isolated limb perfusion (ILP) model using soft tissue sarcoma-bearing rats was used to study prerequisites for an effective ILP, such as oxygenation of the perfusate, temperature of the limb, duration of the perfusion and concentration of tumour necrosis factor (TNF)." (PMID 10389992, 1999).
soft tissue sarcoma (continued). "Isolated limb perfusion with TNF-alpha and melphalan (TM-ILP) in combination with complete tumor resection is an effective treatment option for non-resectable soft-tissue sarcoma of the extremities, with limb salvage rates greater than 80%." (PMID 28403880, 2017).
acute GVHD (32 papers, 2005 to 2025). "Although the Th1 cell‐associated cytokines IFN‐γ, IL‐2 and TNF‐α have been implicated in the pathophysiology of acute GVHD, some studies have reported the opposite effects." (PMID 35844683, 2021). "Based on the cytokine profile, the Th1 cytokines (IFN-γ, IL-2, and TNF-α) have been implicated in the pathophysiology of acute GVHD." (PMID 25541735, 2014). "In the third stage, cellular and inflammatory factors are released, including TNF-α, IL-1, IL-6, IL-10, IL-12, which underlie the clinical manifestations of acute GVHD." (PMID 23802653, 2013). "Alpha-1 Antitrypsin (AAT), a serine protease inhibitor modulates inflammatory response of ECs to TNFα and enhances T regulatory cell recovery in experimental mouse models of acute GVHD." (PMID 36505438, 2022). "Circulating pro-inflammatory cytokines such as TNFα, IFNγ, IL-1, and IL-6 are elevated during acute GVHD and can activate ECs." (PMID 36505438, 2022). "One such agent is infliximab, an anti-TNFα monoclonal antibody that has been studied in prophylaxis, and treatment of steroid-refractory acute GVHD (SR-aGVHD)." (PMID 32411139, 2020). "While all of these cytokines have been shown to be critical sources of Signal 3, agents that block TNF, IL-6, and IL-1, as well as the T cell-derived growth factor IL-2 have been studied as potential modes of treatment in acute GVHD." (PMID 32411139, 2020). "Cytokines like TNF-α and IL-2 which play critical roles in the development of acute GVHD were also regulated by hydrogen." (PMID 31871547, 2019). "TNFα blockade was previously proven to ameliorate acute GVHD in combination with other immunosuppressive drugs." (PMID 30723481, 2018). "Inflammatory cytokines such as IFN-γ, TNF-α, and IL-1 are markedly increased in patients affected by acute GVHD, which potentially explains why clinical efficacy has been more conclusively demonstrated when there are mores severe manifestations of acute GVHD." (PMID 28671556, 2017). "Paradoxically, IL-10, which is thought to inhibit the synthesis of inflammatory cytokines such as IL-8 and TNF-α, was elevated in patients with acute GVHD in our results." (PMID 28881843, 2017). "Th1 cell-associated cytokines involved in acute GVHD include interferon (IFN)-γ, interleukin (IL)-1, IL-6, and tumor necrosis factor (TNF)-α." (PMID 23840617, 2013). "Interleukin-1 and TNF-α also play a central role in the development of acute GVHD, but drugs that target these cytokine/chemokine-receptor interactions (etanercept, infliximab) failed to improve incidence rates of acute GVHD." (PMID 23802653, 2013). "Thirdly, several TNF inhibitor are also available, and a recent study, including 97 patients, suggested that prophylactic use of the TNF inhibitor, etanercept, can reduce the incidence and severity of acute GVHD." (PMID 23430540, 2013). "The recipient mice develop acute GVHD within the first week after transplantation, and the maximum serum levels of IFNγ, TNFα and IL2 are reached at day 5 post transplantation." (PMID 23593203, 2013). "Previous work has shown that IL-2, IL-6, TNF-α and IFN-γ secretion is associated with acute graft-versus-host disease, whilst increased circulatory levels of IL-6 have been associated with chronic graft-versus-host disease." (PMID 20718971, 2010). "TNF-alpha and IFN-gamma cause further injury to the gastrointestinal epithelium leading to the tissue damage characteristic of acute GVHD." (PMID 19448368, 2009). "Together these results confirm the critical role of IL-2 in initiating acute GVHD and demonstrate that TNF, an IL-2 dependent cytokine in this context, is necessary and sufficient to drive CD8 SLEC maturation in the absence of significant levels of inducers of IFNα or IL-12." (PMID 38915570, 2024). "In addition, in vitro models demonstrate that DF can reduce adhesion molecule expression on ECs or leukocyte adhesion in the context of inflammation engendered by sera from patients with acute GVHD or TNFα respectively." (PMID 37441074, 2023).
acute GVHD (continued). "The high serum concentrations of TNF-α characterize acute graft-versus-host disease (aGVHD), for which infliximab treatment may be beneficial." (PMID 37509268, 2023). "TNF-α, a pleiotropic inflammatory cytokine involved in the pathogenesis of rheumatoid arthritis, psoriasis, inflammatory bowel disease, and cancer also plays a role in acute GVHD." (PMID 34899738, 2021). "The main effectors of acute GVHD are donor CD4+ and CD8+ T cells, the latest causing tissue damages through expression of FAS ligand and release of granzyme B, perforin and cytokines such as tumor necrosis factor-alpha (TNFα)." (PMID 31001253, 2019). "Further, increases in several cytokines could trigger kidney injury in acute GVHD; when acute GVHD occurred, interleukin (IL)-2, IL-6, or tumor necrosis factor-α was upregulated in the kidney." (PMID 30842899, 2019). "In addition, several clinical studies have targeted TNF-α as part of a treatment strategy for acute GVHD." (PMID 25541735, 2014). "A polymorphism in the TNF-α gene was demonstrated to increase incidence of severe acute GHVD, but polymorphisms in IL-10, which was considered as suppressing TNF-α, IL-1, and other inflammatory cytokines, was demonstrated with the ability to decrease incidence of acute GVHD." (PMID 23802653, 2013). "In B6→F1 acute GVHD, B6 donor CD4 T cells produce a strong initial IL-2 response, which in turn promotes a Th1-dominant response consisting of robust TNF and IFNγ production." (PMID 38915570, 2024). "Injection of GMSCs into mice with acute GVHD significantly reduced the percentages of cells secreting pro-inflammatory cytokines such as IFN-γ, IL-17, IL-4, and TNF-α." (PMID 30622237, 2019). "It has been found that TNF-α and γ-rays can increase MICA expression by activating the NFκB and JNK pathways in acute graft-versus-host disease, leading to graft damage." (PMID 30013574, 2018). "Clinical trial investigating the combination of TNFα monoclonal antibody (Etanercept) plus methylprednisolone as initial therapy for GVHD found substantial majority of remission, delayed onset of acute GVHD and reduced organ damage." (PMID 30631325, 2018). "Acute GVHD has been proposed to be mediated by Th1-type cells and their inflammatory cytokines including IFN-γ, IL-2 and TNF-α." (PMID 23593203, 2013). "Prevention of acute GVHD by SD-36 treatment of WT T cells was associated with lower serum concentrations of IFN-γ, TNF-α, and IL-6, but not IL-2, and was confirmed by histopathology." (PMID 37526084, 2023). "Cytokines like tumor necrosis factor (TNF)-α, interleukin- (IL-) 1, and IL-6 may directly attack various host tissues which lead to the clinical manifestations of acute GVHD." (PMID 31871547, 2019). "To determine whether GMSCs could suppress acute GVHD through controlling cytokine production by staining with IFN-γ, IL-17, IL-4, TNF-α, IL-2, and IL-10, we detected the production of cytokines after injecting 15 days." (PMID 30622237, 2019). "The “acute GVHD” cluster was defined by an IFN aggregate (A28), inflammation aggregates (A33,35), other aggregates with no known definition (25, 30, 31 and 32), and modules pertaining to the following functions: TNF (in A18), neutrophils/neutrophil activation (in A38), and prostanoids (in A34)." (PMID 40075650, 2025).